CRP (C-reactive protein)
Diseases named in the same sentence as CRP in open-access papers (continued):
Sharing a sentence is not in itself a finding about the gene and the disease.
cancer (continued). "In this regard, increased CRP levels have shown to be associated with tumor growth irrespective of the type of cancer." (PMID 31936329, 2020). "Since CRP affects the metastatic ability of cancer cells this could represent another potential avenue whereby PD interacts with OSCC." (PMID 35047982, 2020). "Higher CRP level was associated with male, higher white blood cell count, lower BMI and albumin, ever smoking, later cancer stage and non-resection." (PMID 31148582, 2019). "Thus, CRP levels were significantly elevated in colorectal and breast cancer patients compared to controls." (PMID 31110819, 2019). "In the present study, dogs with cancer had higher ECPKA‐Ab levels than those without cancer and a combination of the ECPKA‐Ab and CRP levels had increased the diagnostic accuracy for detecting cancer." (PMID 30411459, 2019). "The results of the present systematic review show that in approximately 10,000 patients with cancer, there was a consistent association between CT-derived SMI/SMD and systemic inflammation, as evidenced by CRP, albumin (mGPS) and Neutrophil Lymphocyte Ratio (NLR)." (PMID 31487957, 2019). "We did not observe a significant association between CRP and cancer mortality overall or by race, similar to other published studies using prospective cohort data." (PMID 31448052, 2019). "Our study did not have specific restriction on cancer stage but also observed a strong positive association between CRP/Alb ratio and the mortality of patients with NSCLC." (PMID 31148582, 2019). "In this study, we conducted a meta-analysis and combined the results of relevant studies to evaluate whether pretreatment serum CRP level could serve as a reliable independent prognostic indicator for cancer-specific survival of STS patients." (PMID 31260491, 2019). "There was a significant positive correlation between the neoplastic index, which was developed using ECPKA‐Ab and CRP levels, and the presence of cancer in dogs (P < 0.001); the area under the receiver‐operating characteristic curve was estimated to be >0.85 (P < 0.001)." (PMID 30411459, 2019). "Of course, the CRP level not only reflects inflammation of the skin but also of the whole body; the CRP level can change for various reasons including bacterial superinfection and cancer progression." (PMID 31221161, 2019). "Sensitivities for cancer were 46.1% for CRP, 43.6% ESR and 49.7% for PV." (PMID 31015558, 2019). "Multiple studies have shown the predictive value of CRP in cancer outcomes." (PMID 31138314, 2019). "Secondly, even though we excluded patients from the study who demonstrably suffered from current infections or carcinomas, it is possible that undiagnosed illnesses may have affected CRP levels." (PMID 31788733, 2019). "Similarly, in a study of 471 cancer patients with solid tumors, those with CRP >10 mg/L had less muscle and lost more muscle during the disease trajectory." (PMID 30189611, 2018). "IL-6, similar to many core inflammatory factors, is increased by a large amount in the inflammatory microenvironment of cancer cells; this occurs through the induction of CRP, which activates the NF-κB pathway to reduce the activity of caspase-3 and inhibit the apoptosis of cancer cells." (PMID 30647533, 2018). "More recently, several publications demonstrated that the CRP/Alb ratio could be used to predict the prognosis of several cancers, and two additional studies confirmed the prognostic value of the CRP/Alb ratio in RCC patients." (PMID 29890986, 2018). "We found that the HDL levels were low in cancer patients and the triglyceride and CRP levels high." (PMID 29941786, 2018). "Thus, raised levels of systemic inflammatory markers, such as the C-reactive protein (CRP), are associated with increased all-cause mortality, cancer, and cardiovascular death." (PMID 29696082, 2018). "Although the exact functional mechanism of CRP in the development of cancer remains obscure, several hypotheses have been proposed to explain this relationship." (PMID 29668751, 2018).
cancer (continued). "The significance of establishing the presence of CRP cycles is that it opens up avenues for exploring the efficacy of cancer-based therapies as a function of their timing relative to the biological fluctuations in the immune response occurring in the individual cancer patient." (PMID 30097610, 2018). "In addition, there is increased evidence that a CRP level of 0.3 mg/dl is a significant threshold for predicting the prognosis in both cancer and non-cancer patients." (PMID 30651931, 2018). "CAR is calculated from serum albumin and CRP levels and was first developed to predict outcomes in patients with acute medical admissions, and has recently gained attention as an inflammation-based marker for predicting outcomes in cancer patients." (PMID 30034622, 2018). "Measurement of IL-1β and IL-6 may help identify early cancer progression among patients with CRP < 5 mg/L in routine practice." (PMID 29949857, 2018). "The study demonstrated that elevated levels of CRP in individuals without cancer represent a risk factor for the development of a type of cancer." (PMID 30539028, 2018). "Clinical studies investigating the role of CRP in predicting cancer patient outcomes." (PMID 29619344, 2018). "Moreover, different markers of inflammation, such as cytokines, C-reactive protein, and NLR, are often elevated in patients with cancer and are associated with poor survival." (PMID 30442190, 2018). "Previous studies have shown that statins, CRP‐lowering drugs, have antitumor proliferative, antitumor angiogenic, and antitumor metastatic properties, and therefore, represent a novel treatment method for cancer prevention and treatment." (PMID 29193777, 2018). "However, in our subgroup analysis excluding cancer patients, the CRP/albumin ratio was also an independent predictor of 28-day mortality in the multivariate analysis." (PMID 30297655, 2018). "Elevated C-reactive protein (CRP) levels are related to more advanced disease in cancer patients that undergo palliative RT, but as far as we know no studies demonstrate a relationship between the level of CRP or other inflammatory markers and RT response in patients with CIBP." (PMID 30266081, 2018). "Secondly, CRP/ALB ratio for cancer patients should also be considered." (PMID 29495423, 2018). "Serial measurements to establish CRP kinetics may be clinically useful in different solid tumors and perhaps hematological malignancies and predict clinical course, cancer recurrence and survival." (PMID 30138391, 2018). "The CRP/ALB ratio was initially used as a novel prognostic factor in patients with cancer." (PMID 29495423, 2018). "Furthermore, research suggests that markers of systemic inflammation, such as C-reactive protein (CRP), can predict poor prognosis in patients with cancer." (PMID 29624591, 2018). "Second, although serum CRP concentration is an established predictive factor for many kind of diseases, including cancer and cardiovascular diseases, particularly when assayed by the high-sensitivity method, it is easily changed by acute infection or other cause of inflammation." (PMID 29439678, 2018). "C-reactive protein is an acute temporal response protein, which reflects acute trauma or the inflammatory condition of the patient, instead of the local or systemic inflammation status when cancer is present." (PMID 30419863, 2018). "Moreover, initial reports also suggest that elevated levels of D-dimer, C-reactive protein, and F1 + 2 are risk factors for VTE in patients with cancer." (PMID 29682191, 2018). "When all samples were considered, CA19-9 (P = 0.002), ALP (P = 0.006), GGT (P = 0.039) and CRP (P = 0.0007) were significantly elevated in BTC pre-diagnosis samples compared to cancer-free controls, as was the proportion of samples with CA19-9 levels > 37 U/mL (P = 0.038)." (PMID 29707118, 2018). "However, CRP and s-alb can be considered valid markers of systemic inflammation and also as a part of the criteria for cancer cachexia." (PMID 29534089, 2018).
cancer (continued). "If we consider both, pre‐operative CRP and fibrinogen, as surrogates for inflammatory response, our results could be explained by the concept of systemic inflammation in cancer." (PMID 29701260, 2018). "Increased CRP level has been reported in many types of cancers." (PMID 28264659, 2017). "Previous studies investigated that C-reactive protein (CRP) and albumin levels may represent potential prognostic markers in various cancers." (PMID 28740506, 2017). "In many human cancers, CRP has a role as a prognostic predicting factor." (PMID 28209200, 2017). "Further, elevated CRP and IL-6 are associated with CACS in advanced cancer." (PMID 28384249, 2017). "As we know, CRP is influenced by various non-cancer related conditions." (PMID 28968977, 2017). "Biomarkers of inflammation, such as C-reactive protein (CRP), neutrophil count (NC), and neutrophil-to-lymphocyte ratio (NLR), have been studied as important tools for risk stratification in cancers associated with increased tumor burden and aggressive tumor biology." (PMID 28969089, 2017). "The link between inflammation and cancer is well-recognized; prolonged exposure to proinflammatory cytokines may eventually result in the induction of CRP synthesis and is considered to be a prognostic factor in NPC." (PMID 28874126, 2017). "Recently, CRP/Alb ratio has been used to predict the prognosis of several cancers." (PMID 28264659, 2017). "In recent years, many studies have investigated the most commonly used measures of the systemic inflammatory response, such as C-reactive protein, the Glasgow Prognostic Score, cytokines, and leucocytes, and their potential prognostic impact in cancer patients." (PMID 28830378, 2017). "As we know, both CRP and SCC may influenced by various non-cancer related conditions, and combination of CRP and SCC could therefore minimise the potential basis." (PMID 28968977, 2017). "Stratification analyses of ethnicity, type of cancer, and genotype method also did not obtain any association between CRP gene rs1205 polymorphism and CRC risk." (PMID 28706007, 2017). "There was a similar relationship between CRP elevation and tumor status for each cancer subsite." (PMID 28209200, 2017). "Cancer is always accompanied by inflammatory processes, creating a tumor microenvironment that leads to tumor angiogenesis, invasion, and metastasis through the recruitment of regulatory T-lymphocytes, activation of cytokines, and the secretion of CRP." (PMID 28740506, 2017). "The prognostic relationship with serum CRP levels in cancer patients is probably a complicated and multifactorial process that is still not well understood, but it seems likely that inflammatory cytokines might mediate the relationship." (PMID 29259311, 2017). "CRP/Alb, which is obtained from the combination of CRP and albumin, may reflect both the inflammatory and nutritional state in cancer patients." (PMID 28431566, 2017). "In the NHANES III study and another study within the AMORIS cohort, a quantitative score, ranging from 0-4, derived by adding a number of biomarkers (CRP, albumin, gamma-glutamyl transferase, and HDL cholesterol) with abnormal values was positively associated with cancer mortality." (PMID 26860264, 2016). "Elevated CRP concentrations have been correlated independently with tumor load and disease progression, which have also been shown to correlate with survival in various cancers." (PMID 26980738, 2016). "In age-adjusted analysis (model 1), men within the highest quartiles of CRP (RR = 1.49, 95 % CI 1.20-1.86, p-trend = 0.01) and leukocyte count (RR = 1.64, 95 % CI 1.32-2.03, p-trend = 0.01) had higher risks of cancer compared to those within the lowest quartiles." (PMID 26860264, 2016).
cancer (continued). "The mechanism that causes the increase in serum concentrations of CRP in cancer patients is not clear." (PMID 27082589, 2016). "This may signify differential roles between leptin and CRP in the scope of cancer, which require further biological investigations." (PMID 26632325, 2016). "In the age-adjusted model, the HRs of cancer mortality comparing men within the fourth quartile of CRP and leukocyte count to those within the first quartile were 1.65 (95 % CI 1.18-2.31, p-trend = 0.02) and 2.09 (95 % CI 1.52-2.89, p-trend = 0.01), respectively." (PMID 26860264, 2016). "In sex-stratified analysis, men within the highest CRP levels had a non-statistically significant 1.17-fold increased risk of cancer death compared to men with low levels of CRP, similar to what we observed in our study (RR = 1.23)." (PMID 26860264, 2016). "At 5 days after surgery, normal CRP levels (±5.0 mg/l) were observed in 4 out of the 75 (5%) CD patients, in 20/50 (40%) patients undergoing appendectomy (group B) and in 6/50 (12%) patients undergoing right colectomy for cancer (group C)." (PMID 27551522, 2016). "In summation, it appears the pre-operative CRP level may be useful prognostic predictor in many cancer patients who have undergone a radical treatment to remove the cancer." (PMID 27733196, 2016). "Increased level of CRP and necrotic change suggested the possibility of malignant tumor." (PMID 27923374, 2016). "Secondary outcomes were postoperative complications, cancer recurrence, or metastasis within 1 year after surgery, and postoperative inflammatory responses measured by white blood cell count, neutrophil percentage, and C-reactive protein." (PMID 27175664, 2016). "However, to our knowledge, no study so far has assessed the clinical significance of the CRP/PNI ratio in other cancers as well as EC." (PMID 27557504, 2016). "Measurement of IL‐1β, IL‐6, and TNFα serum levels may help identify early cancer progression among patients with CRP <5 mg/L in routine practice." (PMID 26799163, 2016). "We found a lack of association between leptin and cancer death, whereas CRP was positively associated to cancer death in men." (PMID 26632325, 2016). "Increasing age, hospital admission, no history of cancer, high C-reactive protein (>10mg/l), neutrophil count were independently associated with an increase in cerebrovascular mortality (all p<0.001)." (PMID 25730322, 2015). "Additionally, several studies have indicated that the levels of C-reactive protein (CRP) correlates with the disease progression in a number of cancers." (PMID 26084991, 2015). "Blood levels of CRP are also moderately elevated during chronic inflammatory diseases and cancer." (PMID 26380255, 2015). "Consequently, several biomarkers have been reported to reflect the link between inflammation and cancer, such as interferon-gamma/interleukin-4 ratio and inflammation-based prognostic score (Glasgow prognostic score) based on CRP and albumin levels." (PMID 25885254, 2015). "We hypothesized that merging CRP and albumin into a new index may have prognostic value in inflammation, and better predict overall survival of patients with cancer." (PMID 26084991, 2015). "In addition, this study confirms previous findings that low albumin and increased CRP levels are useful markers for survival time in palliative cancer patients." (PMID 26018761, 2015). "In this study, CRP concentration was significantly higher in cachectic cancer patients." (PMID 26053616, 2015). "In cancer patients, plasma CRP levels are typically high compared with healthy subjects." (PMID 25624919, 2015). "There are three potential mechanisms linking CRP to cancers." (PMID 25999661, 2015). "Elevated CRP in serum represents a systemic inflammatory response, which may indicate much inflammatory mediators from cancer tissue." (PMID 26235332, 2015).
cancer (continued). "In recent years, the Glasgow Prognostic Score (GPS), which consists of two predictors, namely, C-reactive protein (CRP) and albumin, has been found useful for predicting long-term mortality primarily in cancer patients in the outpatient or pre- and postsurgical settings." (PMID 25861154, 2015). "Some studies have compiled the possible roles of CRP in cancer development." (PMID 25970775, 2015). "Recently, in an effort to rationalise and consolidate the literature we have examined the relationship between these markers of the systemic inflammatory response, together with high sensitivity C-reactive protein measurements and platelet counts, and survival in more than 12,000 cancer patients." (PMID 25730322, 2015). "It would thus be interesting to determine whether CRP-SAA could serve as a potential prognostic marker in these cancers." (PMID 26264146, 2015). "The relationship between cumulative markers of the systemic inflammatory response (including high sensitivity C-reactive protein) and mortality in an incidental cohort: Adjusted for age, sex, deprivation, hospital admission and the presence of cancer (n = 52 091)." (PMID 25730322, 2015). "Serum SAA and CRP levels are reported to be elevated in various cancers." (PMID 25884401, 2015). "These proteins, especially CRP, have been extensively investigated in various types of cancer." (PMID 25884401, 2015). "Inadequate screening for known non-cancer CRP-modifying factors may have significantly influenced values." (PMID 26717416, 2015). "A limited pattern of hallmarks of cancer could be clinically monitored, such as inflammation, via CRP response, in RCCC I/II (n = 18; n = 31), in MM (n = 6) and mLCH (n = 2), immune response in one patient with CRPC (CRPC I)." (PMID 26259724, 2015). "It's still unclear that the relationship between CRP and cancer is a causal one, since so many conditions can elevate CRP levels without increasing cancer risk." (PMID 24800842, 2014). "We then assessed whether cancer patients, who have raised inflammation, evident by higher CRP levels relative to healthy individuals, exhibited greater variation in the frequencies of either Tregs or Teffs over time." (PMID 24957270, 2014). "A lag between the expansion phase of effector T cell and regulatory T cell populations could account for the oscillations in CRP levels observed in cancer patients." (PMID 24957270, 2014). "On the other hand, single nucleotide polymorphisms (SNPs) that associate with genetically elevated concentrations of CRP do not confer an increased cancer risk to the general population." (PMID 25025473, 2014). "There was also a direct correlation between the inflammatory markers (ferritin and CRP) and hepcidin in the AC patients, suggesting a role of inflammation-induced hepcidin increase in the pathogenesis of AC in a subset of cancer patients with prominent inflammation." (PMID 24681760, 2014). "By contrast, high sensitivity C-reactive protein was independently associated with cardiovascular mortality but not with cancer mortality in men." (PMID 23984981, 2013). "The cancer patients in this cohort displayed significant signs of inflammation (elevated CRP levels) that could contribute to changes in platelet reactivity." (PMID 24156029, 2013). "Based on these reports, GPS, incorporating CRP and serum albumin levels, may reflect both presence of the systemic inflammatory response (CRP), and the progressive nutritional decline (albumin) in patients with cancers, resulting in poor survival outcome." (PMID 23374755, 2013). "Some studies have compiled the possible roles of CRP in cancer development as follows: i) anti-apoptotic activity and tumorigenic potency by over expression of IL-6, ii) T cell impairment, iii) resistance to chemotherapy, and iv) increased levels of serum angiogenic factors." (PMID 23409924, 2013). "This implies that the factors affecting the CRP levels may be different between cancer patients and healthy population." (PMID 23724031, 2013).